GYS2 (glycogen synthase 2)
Description:
Glycogen synthase participates in the glycogen biosynthetic process along with glycogenin and glycogen branching enzyme. Extends the primer composed of a few glucose units formed by glycogenin by adding new glucose units to it. In this context, glycogen synthase transfers the glycosyl residue from UDP-Glc to the non-reducing end of alpha-1,4-glucan.
Tractability: PROTAC: ubiquitination databases record sites on it; its protein half-life has been measured; a small molecule that binds it is known.
Target class: Enzyme; Transferase
Gene: Protein-coding gene on chromosome 12 (21,536,107 to 21,604,917, reverse strand). Ensembl gene ENSG00000111713.
Pathways (Reactome):
Disease: Glycogen storage disease type 0 (liver GYS2); Glycogen storage disease type IV (GBE1)
Metabolism: Glycogen synthesis
Gene Ontology:
Molecular function: alpha-1,4-glucan glucosyltransferase (UDP-glucose donor) activity; glycogen synthase activity, transferring glucose-1-phosphate
Biological process: glycogen biosynthetic process; response to glucose
Cellular component: cell cortex; cortical actin cytoskeleton; cytoplasm; cytoskeleton; cytosol
Genetic constraint (gnomAD): Loss-of-function variants: 55 observed, 53.92 expected, observed/expected ratio (o/e) 1.02, 90% interval 0.82 to 1.28. The upper end of that interval is the gene's LOEUF score, 1.28, which puts it in group 5 of 6, group 1 being the genes least tolerant of losing a copy. Missense variants: 658 observed, 658.72 expected, observed/expected ratio (o/e) 1, 90% interval 0.94 to 1.07. Synonymous variants: 247 observed, 236.14 expected, observed/expected ratio (o/e) 1.05, 90% interval 0.94 to 1.16.
Gene-disease validity (ClinGen):
ClinGen rates the evidence that GYS2 causes each of these diseases.
glycogen storage disorder due to hepatic glycogen synthase deficiency (autosomal recessive): Definitive.
Homologues: Orthologues: chimpanzee GYS2 (99% identical), macaque GYS2 (98% identical), dog GYS2 (96% identical), pig GYS2 (96% identical), mouse Gys2 (94% identical), rat Gys2 (94% identical), rabbit GYS2 (93% identical), guinea pig GYS2 (83% identical), zebrafish gys2 (78% identical), Drosophila melanogaster Glys (57% identical), Caenorhabditis elegans gsy-1 (51% identical). Paralogues in human: GYS1 (71% identical).
Diseases named in the same sentence as GYS2 in open-access papers:
GYS2 is named in the same sentence as 32 diseases in open-access papers, as found by Europe PMC text mining. Sharing a sentence is not in itself a finding about the gene and the disease. The quoted sentences say what the papers report.
glycogen storage disease type 0 (8 papers, 2010 to 2024). "In humans, GYS2 has been associated with glycogen storage disease type 0, obesity and polycystic ovary syndrome." (PMID 38844868, 2024). "Glycogen storage disease type 0 (GSD0) is an autosomal recessive disease presenting in infancy or early childhood caused by mutations in the GYS2, a gene located on chromosome 12p 12.2 composed of 16 exons which codes for the hepatic isoform of glycogen synthase (GS)." (PMID 20051115, 2010).
hepatocellular carcinoma (8 papers, 2010 to 2025). A malignant tumor that arises from hepatocytes. "glycogen synthase 2 (GYS2) was demonstrated to participate in a feedback loop which restricted HBV-Related Hepatocellular Carcinoma growth." (PMID 32489319, 2020). "The deregulation of glycogen metabolism in hepatocellular carcinoma was recently documented through the downregulation of GYS2 expression, which was correlated with unfavorable patient outcomes." (PMID 33207594, 2020). "As an example of this, the Gys2 and Oat genes were down-regulated in a time-dependent manner in hepatoma cells following Tcf7l2-silencing, and each displayed clear reductions in proximal TCF7L2 binding at 15 h." (PMID 25414334, 2014). "Since GS activity is an absolute requirement for glycogen synthesis, we next investigated the effect of knocking down GYS1 in the hepatoma HepaC1 cells, which also express the liver isoform GYS2." (PMID 20300197, 2010). "Furthermore, we have demonstrated that glycogen synthase 2 (GYS2) depletion leads to downregulation of hepatocellular carcinoma glycogen and accelerate tumor proliferation." (PMID 32802186, 2020). "Genes regulating glycogen metabolism (Gys2), glycolysis (Aldob and Eno2) and glucose transport (Slc2a2) were all affected by Tcf7l2 silencing in the hepatoma cells, suggesting that TCF7L2 activity is an important determinant of carbohydrate metabolism overall in the liver." (PMID 25414334, 2014). "To determine which reader proteins mediate the mRNA stability of Gys2, we independently depleted the six candidate readers in Hepa 1-6 (mouse hepatocellular carcinoma) cells and found that depletion of only IGF2BP2 reduced Gys2 mRNA expression." (PMID 36396934, 2022). "It has been reported that GYS2 acted as a tumor suppressor in hepatocellular carcinoma (HCC)." (PMID 33954109, 2021). "We also highlight similar effects at the ornithine aminotransferase (Oat) and liver-specific glycogen synthase (Gys2) genes, indicating that these metabolic genes also are direct TCF7L2-regulated genes in hepatoma cells." (PMID 25414334, 2014).
Obesity (7 papers, 2011 to 2025). Accumulation of substantial excess body fat. "Published transcriptomic data reveal a downward trend in GYS2 gene expression in patients with obesity, MASLD, and metabolic dysfunction-associated steatohepatitis." (PMID 41407267, 2025). "In humans, GYS2 has been linked to polycystic ovary syndrome and obesity-related conditions." (PMID 40000939, 2025). "The GYS2 gene on chromosome 12p12.2 was identified in a PCOS/GWAS investigation of obesity-related conditions and has lately been confirmed by associations in an independent childhood obesity study." (PMID 33805313, 2021). "Notably, GYS2 gene expression displayed a gradual reduction in patients with obesity, MASLD, and MASH." (PMID 41407267, 2025). "In the first, three novel SNPs in the glycogen synthase 2 (GYS2) gene on chromosome 12p12.2 were identified as being associated with PCOS through investigation of individuals with obesity-related condition; however, none of these variants reached the genome-wide significance threshold." (PMID 33746952, 2021). "Selected candidate genes Npr3 and Thbs1, as well as Gys2, a non-QTL gene that otherwise passed our enrichment criteria were characterised, revealing novel functional effects consistent with a contribution to obesity." (PMID 21915269, 2011).
Hypoglycemia (5 papers, 2010 to 2023). A decreased concentration of glucose in the blood. "However, they may suggest that in presence of predisposing conditions, carriers of GYS2 mutations might be at increased risk of developing hypoglycemia." (PMID 20051115, 2010). "Biochemical evaluation as well as direct sequencing of exons and exon-intron boundary regions of the GYS2 gene were performed in a patient presenting fasting hypoglycemia and postprandial hyperglycemia and her parents." (PMID 20051115, 2010). "The patient 120 is possibly a GSD patient because he presented clinical symptoms such as hypoglycemia and ketonuria but no other clinical signs, however only synonymous variants were found in GYS2 (that causes GSD type 0), which does not justify the disease." (PMID 31508908, 2019).
Hyperglycemia (4 papers, 2010 to 2023). An increased concentration of glucose in the blood. "To assess directly the causal link between hepatic glycogen accumulation and the exacerbation of hyperglycemia, we performed glycogen replenishment analysis for the liver of fasted ob/ob HKO mice infected with an adenovirus vector encoding GS (encoded by Gys2)." (PMID 37681411, 2023). "While these data do not correspond to the observed increase in plasma glucose, the fact that fish were sampled 5 d following the last injection of the LNA-122i may reflect that the induction of gys2 represents a counter-regulatory response to cope with hyperglycemia." (PMID 24467738, 2014).
diabetes (3 papers, 2013 to 2025). "LBP also prevented the decrease in glycogen synthase (GYS2) mRNA expression and the reduction of liver glycogen content in diabetes mellitus (DM) mice." (PMID 40994658, 2025). "Loci for the other genes—PTP4A1, APOBR, BMS1P4-AGAP5, MAPK8IP1P1, GYS2, FAM25C, and GK5–were formerly associated with traits involved with comorbidities of OSA, i.e., BMI, weight, triglycerides, blood pressure, stroke, brain volume, cortical thickness, mood, insulin, and diabetes." (PMID 39457448, 2024).
Glycogen storage disease type 0a (2 papers, 2023 to 2024). "GSD type 0a is a relatively uncommon subtype caused by mutations in the GYS2 gene, with an estimated incidence of <1 per million individuals." (PMID 39121286, 2024). "GSD type 0 is caused by mutations in the GYS1 gene, leading to muscle glycogen synthase deficiency, and mutations in the GYS2 gene, leading to liver glycogen synthase deficiency." (PMID 37601653, 2023). "GSD Type 0, also known as Glycogen synthase deficiency (Muscle glycogen synthase deficiency (encoded by GYS1) and liver glycogen synthase deficiency (encoded by GYS2))." (PMID 37601653, 2023). "Glycogen storage disease type 0a (GSD0a, OMIM#240600) is an autosomal recessive disorder caused by a deficiency in glycogen synthase (GS), encoded by the GYS2 gene." (PMID 39121286, 2024).
Hepatic (2 papers, 2020 to 2022). "Logically, if the METTL3-IGF2BP2-GYS2 axis exists in cells, reconstitution of GYS2 would rescue Mettl3-cKO-associated hepatic glycogen deficiency." (PMID 36396934, 2022).
Insulin resistance (2 papers, 2021 to 2023). Increased resistance towards insulin, that is, diminished effectiveness of insulin in reducing blood glucose levels. "Disruption of GYS2 is known to result in impaired glucose deposition and hepatic insulin resistance and liver fat accumulation in mice by changing de novo lipogenesis through increased expression of SREBP1c." (PMID 33962692, 2021).
steatosis (2 papers, 2021 to 2024). Increased lipid within the cytoplasm of cells. "However, the results obtained for other genes negatively associated with serum ferritin in this cohort with steatosis seemed counterintuitive (GYS2, SEC24B, SOCS2)." (PMID 33962692, 2021). "In addition to modulating the core clock, (+)‐catechin rescued the expression of key other metabolic genes, such as Gk, Gys2, and Acaca, which were disrupted by steatosis." (PMID 39523911, 2024).
cholangiocarcinoma (1 paper, 2021). A carcinoma that arises from the intrahepatic biliary tree (intrahepatic cholangiocarcinoma) or from the junction, or adjacent to the junction, of the right and left hepatic ducts (hilar cholangiocarcinoma). "In this work, based on the results of an integrated pan-cancer analysis of GYS2 in GEPIA database strongly suggested that the gene was significantly down-regulated in a variety of tumors, including cholangiocarcinoma." (PMID 34783271, 2021).
hepatobiliary tumors (1 paper, 2021). "We first performed an integrated pan-cancer analysis of GYS2 in GEPIA database, and found that GYS2 was significantly down-regulated in a variety of tumors, especially in hepatobiliary tumors." (PMID 34783271, 2021). "First, we performed an integrated pan-cancer analysis of GYS2 in the GEPIA database and found that the expression of GYS2 was significantly down-regulated in a variety of human tumors, especially in hepatobiliary tumors, compared with corresponding normal tissues." (PMID 34783271, 2021).
liver cancer (1 paper, 2020). An epithelial or non-epithelial malignant neoplasm that arises from the liver. "As glucose-mediated activation of the AMPK/EP300 axis favors EP300/β-catenin association and would be inhibited in the presence of high GYS2, we anticipated that in liver cancer, in which GYS2 levels vary considerably, high GSY2 activity would correlate with reduced β-catenin activity." (PMID 32603375, 2020).
liver fibrosis (1 paper, 2025). "TAK effectively alleviated ASD-induced disruptions in glycogen synthesis via PI3K/AKT/GSK3/GYS2 pathways, abnormal lipid accumulation via SREBP1/FASN/ACC, liver inflammation by balancing M1 and M2 macrophages, and liver fibrosis induced by ASD/CSD." (PMID 40331934, 2025).
lymph node metastasis (1 paper, 2021). "More importantly, through the comprehensive analysis of clinicopathological indicators and follow-up information, we found that the expression level of GYS2 was closely related to pathological grade, tumor size, microvascular invasion and lymph node metastasis." (PMID 34783271, 2021).
non-alcoholic steatohepatitis (1 paper, 2025). "This state is reminiscent to non-alcoholic steatohepatitis (NASH) because of the downregulation of PPARα-related lipid metabolism and inhibition of glycogenesis (GYS2 down), which suggests glucose release or glycolysis (G6P and G6PC3 up, G6PD down)." (PMID 40806595, 2025).
prostate adenocarcinoma (1 paper, 2021). "Another study identified five glycolysis-related mRNAs (GYS2, STMN1, PPFIA4, KDELR3, and ABCB6) which were associated with patients experience biochemical recurrence (BCR) after radical prostatectomy (RP) in patients with prostate adenocarcinoma." (PMID 34489401, 2021).
tumor (7 papers, 2019 to 2022). "When GYS2 was overexpressed, the proliferation, migration and invasion of tumor cells were obviously limited, while when GYS2 was silenced, the reverse trend was observed." (PMID 34783271, 2021). "The expression level of GYS2 was closely related to the pathologic differentiation (P = 0.017), tumor size (P = 0.026), vascular invasion (P = 0.015) and lymphatic metastasis (P = 0.014)." (PMID 34783271, 2021). "The expression levels of B3GALT6, DCN, FBP2 and GYS2 are lower in tumor samples and higher in normal tissue samples." (PMID 32489319, 2020). "The results prove that the expression levels of B3GALT6, DCN, FBP2 and GYS2 are lower in tumor samples and higher in normal tissue samples." (PMID 32489319, 2020). "Consistent with the results in the TCGA cohort, the mRNA expression of CSE1L, CSTB, MMP10 was significantly up-regulated in HCC while GYS2 was significantly down-regulated when compared with non-tumor tissues." (PMID 31139015, 2019). "Based on the integrated pan-cancer analysis of GYS2 in the GEPIA database, the expression of GYS2 in paired ICC and adjacent non tumor tissues was detected by qPCR." (PMID 34783271, 2021). "CLEC1B, GYS2, and CYP2C8 were identified as tumor suppressors for the prognosis, however, EXO1 was determined to be an oncogene." (PMID 34950206, 2021).
cancer (4 papers, 2020 to 2023). A tumor composed of atypical neoplastic, often pleomorphic cells that invade other tissues. "Remarkably, siRNA-mediated GYS2 depletion led to AMPK induction by glucose in liver Hep G2 cancer cells." (PMID 32603375, 2020). "Moreover, an enrichment in other metabolomic targets was identified (GYS2 and NAT8L), which are potential targets as in other cancers." (PMID 37908747, 2023).
infection (2 papers, 2009 to 2019). The state of being infected such as from the introduction of a foreign agent such as serum, vaccine, antigenic substance or organism. "LCMV-infected liver up-regulated expression of glycogen synthase 2 (GYS2) in both pre-viremic and viremic stages of infection suggesting the possibility that glucose storage was enhanced." (PMID 19216742, 2009). "We also found that hepatic glycogen content in 12-week-old male LTCFND mice showed a trend of increase, whereas in mouse primary hepatocytes (MPHs), adenovirus Ad-TCF7L2DN infection but not Ad-TCF7L2 infection increased expression of glycogen synthase 2 (Gys2)." (PMID 31589598, 2019).
GYS2 also shares sentences with these, for which no sentence is quoted: polycystic ovary syndrome (2 papers); atherosclerosis (1); bronchial hyperreactivity (1); clear cell renal cell carcinoma (1); glioblastoma (1); hepatitis B infection (1); intrahepatic cholangiocarcinoma (1); Muscle glycogen synthase deficiency (1); Non-Alcoholic Fatty Liver Disease (1); Parkinson disease (1); Stroke (1); type 2 diabetes mellitus (1).